HDAC5 (histone deacetylase 5)
Diseases named in the same sentence as HDAC5 in open-access papers (continued):
Sharing a sentence is not in itself a finding about the gene and the disease.
Stroke (5 papers, 2013 to 2023). Sudden impairment of blood flow to a part of the brain due to occlusion or rupture of an artery to the brain. "Accordingly, both HDAC4 and HDAC5 are predominantly expressed in neurons and increase following stroke injury, especially in neuronal nuclei." (PMID 37298129, 2023). "A recent study showed that the DREAM/HDAC4/HDAC5 complex epigenetically down-regulates ncx3 gene transcription after stroke, and the pharmacological inhibition of class IIa HDACs reduces stroke-induced neurodetrimental effects." (PMID 34360712, 2021). "In adult models of stroke, the use of ephrin-A5 antagonists, GABAα5 inverse agonists, histone deacetylase 5 inhibitors, or C-C chemokine receptor 5 (CCR5) knockdown at delayed time points augmented motor recovery." (PMID 34659399, 2021). "For instance, DREAM recruits histone deacetylase isoform 4 and 5 (HDAC4 and HDAC5) enzymes, leading to the deacetylation of histone H4 on the promoter of NCX3 gene after stroke." (PMID 37298129, 2023).
Insulin resistance (4 papers, 2015 to 2024). Increased resistance towards insulin, that is, diminished effectiveness of insulin in reducing blood glucose levels. "As described in the introduction, PKD1 overexpression protects against lipid-induced insulin resistance in the heart, but also induces the pathological condition of hypertrophic growth via HDAC5 phosphorylation." (PMID 33090289, 2021). "To identify the underlying physiological mechanism of the age-related increased propensity for adiposity, insulin resistance and dyslipidemia in male HDAC5-KO mice, we performed indirect calorimetry measurements at an age of 3 months, i.e. prior to the onset of weight differences." (PMID 39304061, 2024). "Hence, the current study aimed to address these knowledge gaps and investigate the effects of 8 weeks of warm and cold-water swimming exercise with cinnamon consumption on serum levels of METRNL, histone deacetylase-5 (HDAC5), and insulin resistance in diabetic male rats." (PMID 38681576, 2024). "Collectively, we conclude that PIMT mediates TNF-α induced insulin resistance at the skeletal muscle via the transcriptional modulation of GLUT4, MEF2A, PGC-1α and HDAC5 genes." (PMID 26468734, 2015). "Hence, this study aims to assess the impact of an eight-week cold-and-warm-water swimming exercise, along with concurrent cinnamon consumption, on the levels of METRNL, Homeostatic Model Assessment for Insulin Resistance (HOMA-IR), and HDAC5 in diabetic male rats." (PMID 38681576, 2024). "At the age of 6 months, male HDAC5-KO mice further showed significantly elevated HOMA-IR levels, indicating insulin resistance, as well as elevated plasma leptin, cholesterol and non-esterified free fatty acids (NEFA) levels." (PMID 39304061, 2024).
non-small cell lung carcinoma (4 papers, 2019 to 2025). A group of at least three distinct histological types of lung cancer, including non-small cell squamous cell carcinoma, adenocarcinoma, and large cell carcinoma. "Our results revealed that HDAC5, a class IIa histone deacetylase (HDAC), is a prominently induced epigenetic regulator in several EGFR-mutant non-small cell lung cancer (NSCLC) cell lines during the early response to osimertinib." (PMID 40290805, 2025). "While the involvement of HDAC5 in EMT is overall poorly studied to date, in accord with our findings, upregulation of HDAC5 was reported to promote EMT in non-small cell lung cancer cells." (PMID 31052182, 2019).
ovarian carcinoma (4 papers, 2023 to 2024). A malignant neoplasm originating from the surface ovarian epithelium. "An overexpression of HDAC5 in ovarian cancer cells inhibits the transcription of IFFO1 and enhances the proliferation, migration and chemoresistance of ovarian cancer cells." (PMID 37894746, 2023). "The eventual correlation between RUNX1T1 and HDAC5 in the acquisition of platinum resistance in ovarian cancer should be studied in detail." (PMID 37686015, 2023). "In this regard, the recruitment of HDAC5 has been described to modulate the novel tumour suppressor IFFO1 that inhibits tumour metastasis and reverses drug resistance in ovarian cancer." (PMID 37686015, 2023).
prostate carcinoma (4 papers, 2021 to 2025). A carcinoma that arises from epithelial cells of the prostate gland. "Among class II HDACs, HDAC-4 and HDAC-5 were significantly overexpressed in prostate cancer tissues and even more in the cases of recurrent prostate cancer." (PMID 34441281, 2021). "Recent studies indicate that HDAC5 inhibitors boost RB1 expression and sensitise CDK4/6 inhibitors in prostate cancer cells." (PMID 40070134, 2025). "HDAC-5 (as well as HDAC-1, -2, -3 and -4) expression in prostate carcinomas is two-fold higher in pT3 compared to pT2 cases and to connect with tumor recurrence and metastasis." (PMID 33799478, 2021).
Sepsis (4 papers, 2016 to 2025). Sepsis is defined as life-threatening organ dysfunction caused by a dysregulated host response to infection. "A recent study showed that decreasing HDAC2 and HDAC5 expression levels were in parallel with increasing acetyl histone H3 and associated with the renoprotective effect of dexmedetomidine in sepsis-induced AKI37." (PMID 27145860, 2016). "DEX reduces sepsis-induced AKI by decreasing TNF-α and MCP-1 and increasing BMP-7, which is associated with decreasing HDAC2 and HDAC5, as well as increasing acetyl histone H3." (PMID 40989844, 2025).
viral infection (4 papers, 2019 to 2024). "FMDV structural protein VP1 degrades histone deacetylase 5 (HDAC5) via the proteasomal pathway, while HDAC5 acts as a positive modulator of IFN-β production during viral infection." (PMID 39350170, 2024). "A possible explanation may be to overcome HDAC5 restriction and to permit virus infection to progress beyond genome replication." (PMID 31067474, 2019). "In conclusion, this study highlights that HDAC5 acts as a positive modulator of IFN-β production during viral infection, while FMDV capsid protein VP1 antagonizes the HDAC5-mediated antiviral immune response by degrading HDAC5 to facilitate viral replication." (PMID 38534383, 2024). "This showed that all the C6 proteins, but not N1, induced degradation of HDAC5 outwith virus infection." (PMID 38461415, 2024).
Anxiety (3 papers, 2014 to 2024). Intense feelings of nervousness, tension, or panic often arise in response to interpersonal stresses. "In the nucleus accumbens (NAcc), chronic social defeat has been shown to significantly decrease the expression of histone deacetylase (HDAC) subtype 5, and mice that lack HDAC5 have been observed to exhibit enhanced depressive and anxiety-like behaviors." (PMID 24618807, 2014). "In motor coordination, total locomotion and elevated plus maze tests, Hdac4b knockout mice displayed deficits in motor coordination as well as hyperactive and less anxiety-like behavior, which could not be observed in Hdac5 knockout mice." (PMID 36946487, 2024).
astrocytoma (3 papers, 2008 to 2024). "Class II HDACs (HDAC5/7/9) downregulation was observed in glioblastomas compared to grade I–II astrocytomas." (PMID 39063083, 2024). "Comparison with low-grade astrocytoma (grades I and II) showed that the expression of 6 of 8 genes was lower in glioblastomas (except for HDAC5 and -7)." (PMID 18713462, 2008).
cervical carcinoma (3 papers, 2019 to 2024). A carcinoma arising from either the exocervical squamous epithelium or the endocervical glandular epithelium. "Finally, we further screened the 2 DE RNAs (AMZ2P1 and HDAC5) closely associated with the development of cervical cancer by clinical sample." (PMID 33833775, 2021). "Finally, AMZ2P1 and HDAC5 were identified to be related to prognosis and cervical cancer development using clinical samples." (PMID 33833775, 2021). "Finally, combined with cluster analysis results, we further screened 2 DE RNAs (AMZ2P1 and HDAC5) using clinical samples, suggesting that AMZ2P1, and HDAC5 may act as diagnostic biomarkers for the development of cervical cancer." (PMID 33833775, 2021). "For example, active participation of histone deacetylases (HDAC1, HDAC5 and HDAC6) in cervical cancer and significant degree made them vital for network maintenance." (PMID 31766427, 2019).
diabetic kidney disease (3 papers, 2018 to 2022). Progressive kidney disorder caused by vascular damage to the glomerular capillaries, in patients with diabetes mellitus. "In contrast to our results, a previous study showed that in diabetic nephropathy, overexpression of HDAC5 significantly attenuated TGF-β1-induced PAI-1 and p21 expression, which indicated the negative regulatory role of HDAC5 in TGF-β1 signaling." (PMID 36263180, 2022). "Taken together it is suggested that HDAC5 is a promising target to ameliorate diabetic kidney disease via regulating EMT." (PMID 33414476, 2021). "Summarily, PI3K/Akt pathway is the upstream signaling pathway to regulate HDAC5 expression in renal tubular cells of diabetic kidney disease." (PMID 33414476, 2021). "Combined with these findings, our experiments suggested that TGF-β1 was the important downstream target of HDAC5-regulated EMT in diabetic kidney disease." (PMID 33414476, 2021).
glioblastoma (3 papers, 2008 to 2024). The most malignant astrocytic tumor (WHO grade IV). "Of particular note, HDAC5 was the onlyclass II member whose expression was reduced in most tumors studied here and robustly so in all of our glioblastoma samples." (PMID 25791281, 2015).
heart failure (3 papers, 2023 to 2025). Inability of the heart to pump blood at an adequate rate to meet tissue metabolic requirements. "Moreover, further exploration of the potential of HDAC5 inhibition as a therapeutic strategy for the treatment of heart failure and ventricular remodeling is warranted." (PMID 37667300, 2023). "The activation of phospholipase C β1 at the nuclear membrane by α1-AR, leading to the release of Ca2+ histone deacetylase 5 (HDAC5) and CAMKII-induced nuclear export, is a central mechanism in the induction of heart failure." (PMID 40129768, 2025). "We provide a better understanding of the molecular mechanisms underlying this interaction may contribute to the development of novel therapeutic strategies targeting HDAC5 and MEF2A for the treatment of heart failure and other cardiovascular diseases." (PMID 37667300, 2023).
Hyperglycemia (3 papers, 2021 to 2025). An increased concentration of glucose in the blood. "All in all, hyperglycemia increases HDAC5 expression in renal tubular cells of diabetic kidney, leading to epithelial–mesenchymal transition." (PMID 33414476, 2021). "In diabetic tubular cells, hyperglycemia enhanced HDAC5 expression, and through elevation of TGF-β1, HDAC5 overexpression led to epithelial-mesenchymal transition in renal tubular cells." (PMID 37841018, 2023).
Hypertension (3 papers, 2018 to 2025). The presence of chronic increased pressure in the systemic arterial system. "HDAC5 and Rho‐associated protein kinase 2 are upregulated in ANG II‐induced hypertension mice, which affect ROS production and mediate vascular hypertrophy, vasoconstriction and oxidative stress in hypertension." (PMID 40497340, 2025). "A key substrate of PKD1 in hypertension-induced cardiac remodeling is histone deacetylase-5 (HDAC5), a member of the HDAC family negatively regulating the acetylation status of nucleosomal histones, and thereby repressing transcription." (PMID 29930945, 2018). "HDAC5 is an early epigenetic regulator of IH‐induced sympathetic activation and hypertension." (PMID 40497340, 2025). "Although the detailed mechanism of LMK235 in the regulation of vasoconstriction remains elusive, pharmacological inhibition of class I HDACs or knockdown of HDAC5 could be a novel therapeutic strategy for the treatment of hypertension." (PMID 30734467, 2019). "In summary, HDAC5 plays an important role in the early pathogenesis and vascular remodelling of ANG II‐induced hypertension, HDAC6 affects vascular relaxation function, while HDAC1 and HDAC2 regulate the transcription of genes related to blood pressure regulators." (PMID 40497340, 2025).
lymph node metastasis (3 papers, 2021 to 2024). "PCR and immunohistochemical analyses have shown that HDAC5 was highly expressed in the cytoplasm of malignant epithelial cells, and HDAC5 expression was positively associated with distant metastasis and lymph node metastasis." (PMID 34178647, 2021). "Interestingly, the presence of nuclear HDAC-5 immunohistochemical positivity was associated with the presence of lymph node metastasis." (PMID 38790909, 2024). "Interestingly, the presence of lymph node metastasis was associated with nuclear HDAC-5 positivity in the entire cohort (Chi-square test, p = 0.048)." (PMID 38790909, 2024). "On the contrary, HDAC-5 nuclear positivity was correlated with lymph node metastasis in the entire cohort (p = 0.048)." (PMID 38790909, 2024).
Obesity (3 papers, 2016 to 2024). Accumulation of substantial excess body fat. "We thus exposed global HDAC5 deficient mice to standard chow diet for up to 7 months and revealed an adult-onset propensity for obesity and comorbid sequelae when compared to wildtype controls." (PMID 39304061, 2024). "The phenotype of obesity and metabolic syndrome observed in our mouse model closely mirrors human genomic studies that demonstrate associations of HDAC5 with whole body fat mass, height, HDL cholesterol levels, apolipoprotein A1 levels, and diastolic blood pressure." (PMID 39304061, 2024). "This suggests HDAC5 could be a target for the treatment of obesity-associated hepatic steatosis." (PMID 34098115, 2021). "Mature-onset obesity has been reported for various murine knockout models, e.g. for IL-1R, IL-6, p62, TLR2 and OTR, and is now also linked with HDAC5 deficiency." (PMID 39304061, 2024). "We had previously shown an accelerated onset of obesity when 8-10-week-old male global HDAC5 KO mice were exposed to HFD feeding." (PMID 39304061, 2024). "Global HDAC5 KO mice have increased food intake and greater diet-induced obesity when fed high-fat diet." (PMID 26923837, 2016). "Genetic and pharmacological manipulations of hypothalamic HDAC5 activity had profound effects on food intake and body-weight control in our studies and overall suggest a beneficial role for selected HDAC5 activation against leptin resistance and obesity." (PMID 26923837, 2016). "Rather, our results indicate that HDAC5 has a specific and important role in the molecular processes leading to HFD-induced obesity and associated hyperleptinemia." (PMID 26923837, 2016). "Consequently, selective HDAC5 activation is a novel and promising approach to counteract leptin resistance and obesity by targeting the primary interactions between dietary challenges and the CNS control of metabolism." (PMID 26923837, 2016). "Consistent with the reduction in Pomc gene expression, we found increased body adiposity and food intake in HFD-fed HDAC5 KO mice, and partial protection from diet-induced obesity in mice with hypothalamic overexpression of HDAC5 relative to the appropriate controls." (PMID 26923837, 2016). "Specifically, we aimed to assess whether HDAC5 deficiency is linked to an increased propensity for obesity and its sequelae in mature mice, even in the absence of an obesogenic environment." (PMID 39304061, 2024). "Hypothalamic HDAC5 overexpression improves leptin action and partially protects against HFD-induced leptin resistance and obesity." (PMID 26923837, 2016). "•Male, but not female, HDAC5 KO mice fed chow develop obesity due to reduced thermogenesis." (PMID 39304061, 2024). "In young mice with global deletion of HDAC5, the exposure to HFD led to impaired expression of the anorexigenic neuropeptide proopiomelanocortin (POMC) that translated into leptin resistance, elevated food consumption and diet-induced obesity, compared to HFD-fed wildtype controls." (PMID 39304061, 2024).
osteoporosis (3 papers, 2011 to 2020). A condition of reduced bone mass, with decreased cortical thickness and a decrease in the number and size of the trabeculae of cancellous bone (but normal chemical composition), resulting in increased fracture incidence. "HDAC5 is transcribed by miR-2861 and in humans, a mutation in pre-miR2861 was found to cause osteoporosis in two adolescents." (PMID 31698700, 2019). "For example, HDAC5 has been shown to be related to RUNX2 degradation, hence decreasing bone formation and accelerating osteoporosis in mice." (PMID 31698700, 2019).
triple-negative breast carcinoma (3 papers, 2018 to 2025). An invasive breast carcinoma which is negative for expression of estrogen receptor (ER), progesterone receptor (PR), and human epidermal growth factor receptor 2 (HER2). "Furthermore, the expression levels of KDM1A and HDAC isozymes are correlated, i.e., KDM1A knockdown induces a decrease in the expression of HDAC5 in triple-negative breast cancer, while the depletion of HDAC5 leads to the accumulation of H3K4me2." (PMID 29921310, 2018).
urothelial carcinoma (3 papers, 2019 to 2024). A malignant neoplasm derived from the transitional epithelium of the urinary tract (urinary bladder, ureter, urethra, or renal pelvis). "We therefore characterized in detail the effects of stable expression of HDAC5 on four urothelial carcinoma cell lines with different phenotypes, which reflect the heterogeneity of the disease." (PMID 31052182, 2019). "In conclusion, according to global gene expression analyses, the class IIA HDAC4 and HDAC5 are both lower expressed in urothelial carcinoma than in normal bladder tissue." (PMID 31052182, 2019).
atrial fibrillation (2 papers, 2022 to 2025). A disorder characterized by an electrocardiographic finding of a supraventricular arrhythmia characterized by the replacement of consistent P waves by rapid oscillations or fibrillatory waves that vary in size, shape and timing and are accompanied by an irregular ventricular response. "In summary, although HDAC1 and HDAC3 are involved in the development of calcium management defects associated with atrial fibrillation, class IIa HDACs such as HDAC5 and HDAC7 provide protection from dysfunction caused by tachypacing." (PMID 40660005, 2025).
autoimmune disease (2 papers, 2015 to 2025). A disorder resulting from loss of function or tissue destruction of an organ or multiple organs, arising from humoral or cellular immune responses of the individual to their own tissue constituents. "Taken together, the present study sheds new light on the role of individual HDAC in the activation of immune cells and appoints HDAC5 as a potential therapeutic target in diseases with massive macrophage activation like modulated as in autoimmune diseases or inflammation-associated cancer." (PMID 26059794, 2015).
HCMV infection (2 papers, 2019 to 2020). "Collectively, these data show that HDAC5 is a restriction factor for two different large DNA viruses, and the biological importance of this is supported by the targeted degradation of HDAC5 during VACV and HCMV infection." (PMID 31067474, 2019). "Furthermore, HCMV infection induced the activity of AMP-activated protein kinase (AMPK), and AMPK could enhance GLUT4 transcription through phosphorylation of histone deacetylase 5 (HDAC5), a transcriptional repressor." (PMID 33271926, 2020).
ischaemic stroke (2 papers, 2013 to 2016). "Our results indicate that forced expression of HDAC4 and HDAC5 decreases not only HMGB1 release but also expression, indicating the contributing role of HDAC4 and HDAC5 on the regulation of HMGB1 function in ischaemic stroke." (PMID 23480850, 2013).
liver cancer (2 papers, 2016 to 2020). An epithelial or non-epithelial malignant neoplasm that arises from the liver. "HDAC5, a Class II HDAC, has been shown to play a critical role in cell proliferation and apoptosis in different cancers, and HDAC5 expression is increased in liver cancer tissues, suggesting that it may be a potential marker of poor patient survival." (PMID 26993777, 2016).